ABLIM3 (actin binding LIM protein family member 3)
Description:
May act as scaffold protein. May stimulate ABRA activity and ABRA-dependent SRF transcriptional activity.
Synonyms: KIAA0843; HMFN1661
Tractability: PROTAC: its protein half-life has been measured.
Gene: Protein-coding gene on chromosome 5 (149,141,483 to 149,260,542, forward strand). Ensembl gene ENSG00000173210.
Subcellular location: Cytoplasm
Subcellular location (Human Protein Atlas): Nucleoplasm; Cytosol
Pathways (Reactome):
Developmental Biology: DCC mediated attractive signaling
Gene Ontology:
Molecular function: protein binding; actin filament binding; actin binding
Biological process: cilium assembly; lamellipodium assembly; positive regulation of establishment of protein localization to mitochondrion; cytoskeleton organization
Cellular component: lamellipodium; stress fiber; actin cytoskeleton; cytoplasm; glutamatergic synapse; synapse
Genetic constraint (gnomAD): Loss-of-function variants: 61 observed, 109.31 expected, observed/expected ratio (o/e) 0.56, 90% interval 0.45 to 0.69. The upper end of that interval is the gene's LOEUF score, 0.69, which puts it in group 2 of 6, group 1 being the genes least tolerant of losing a copy. Missense variants: 794 observed, 923.99 expected, observed/expected ratio (o/e) 0.86, 90% interval 0.81 to 0.91. Synonymous variants: 299 observed, 337.22 expected, observed/expected ratio (o/e) 0.89, 90% interval 0.81 to 0.98.
Homologues: Orthologues: chimpanzee ABLIM3 (99% identical), macaque ABLIM3 (99% identical), dog ABLIM3 (99% identical), rabbit ABLIM3 (98% identical), guinea pig ABLIM3 (98% identical), mouse Ablim3 (98% identical), pig ABLIM3 (97% identical), rat Ablim3 (96% identical), tropical clawed frog ablim3 (82% identical), zebrafish ablim3 (74% identical), Drosophila melanogaster Unc-115a (34% identical), Drosophila melanogaster Unc-115b (32% identical). Paralogues in human: ABLIM1 (53% identical), ABLIM2 (49% identical), DMTN (22% identical).
Diseases named in the same sentence as ABLIM3 in open-access papers:
ABLIM3 is named in the same sentence as 5 diseases in open-access papers, as found by Europe PMC text mining. Sharing a sentence is not in itself a finding about the gene and the disease. The quoted sentences say what the papers report.
Cognitive impairment (1 paper, 2024). Abnormal cognition is characterized by deficits in thinking, reasoning, or remembering. "Additionally, the expression of transcription factor Sp4 was found to increase, which regulated the gene Ablim3 associated with cognitive impairment in the InN1 subpopulation." (PMID 39635132, 2024).
multiple sclerosis (1 paper, 2022). A progressive autoimmune disorder affecting the central nervous system resulting in demyelination. "CYFIP2 is highly abundant in CD4+ cells from multiple sclerosis patients and is involved in T cell adhesion, and ABLIM3 is a component of adherent junctions with actin‐binding activity." (PMID 35124891, 2022).
sarcoidosis (1 paper, 2020). Sarcoidosis is a multisystemic disorder of unknown cause characterized by the formation of immune granulomas in involved organs. "The top most upregulated gene in response to DEX treatment in sarcoidosis monocytes was actin binding LIM protein family member 3 (ABLIM3) (log2 FC = 3.1, FDR = 1.0 × 10−6)." (PMID 32477331, 2020).
cancer (2 papers, 2009 to 2024). A tumor composed of atypical neoplastic, often pleomorphic cells that invade other tissues. "While Lim domain proteins are known to be regulated in embryonic development and in cancer it is postulated that Ablim3 functions as linkage between the actin cytoskeleton and signaling pathways." (PMID 19812696, 2009). "In the blue module (associated with the untreated cancer cells), the enriched pathways were “Cilium Disassembly”, “Microtubule”, “Tubulin Binding”, “Myosin Binding”, and “Lamellipodium Assembly”, where the genes KIF1C, MAP4, ACTG1, ABLIM3, TRIOBP are involved." (PMID 38534323, 2024).
ABLIM3 also shares sentences with these, for which no sentence is quoted: schizophrenia (1 paper).